FASN (fatty acid synthase)
Diseases named in the same sentence as FASN in open-access papers (continued):
Sharing a sentence is not in itself a finding about the gene and the disease.
cancer (continued). "Studies blocked LD formation by inhibiting lipid synthesis pathways such as FASN and found that cancer cells lacking LDs were more prone to apoptosis." (PMID 37474495, 2023). "The synthesis of fatty-acid through fatty-acid synthase could up-regulate DDR and therefore induce cancer cell survival and therapeutic resistance." (PMID 36873527, 2023). "FASN has been shown to be O-GlcNAcylated, which enhances the enzymatic activity of this fatty acid synthesizing enzyme, further supporting the intensive crosstalk between OGT, FASN, and the mTOR pathway in cancer." (PMID 37838167, 2023). "In addition, we considered the close involvement of FASN in antitumor therapeutic resistance, CSC maintenance/survival and cancer cell plasticity." (PMID 36753044, 2023). "Nevertheless, also in this study, FASN was found to be increased on a protein level in cancer tissue when compared to the adjacent nontumor tissue." (PMID 36834678, 2023). "Since we did not directly evaluate FASN expression in the cancer tissue of patients, we cannot conclude that FASN activity is changed in preoperative BC patients." (PMID 37173619, 2023). "ATP-citrate lyase (ACLY), acetyl-CoA carboxylase (ACC), fatty acid synthase (FASN), stearoyl-CoA desaturase-1 (SCD1), 3-hydroxy-3-methyl-glutaryl-CoA reductase (HMGCR), and squalene epoxidase (SQLE) are overexpressed in cancer cells and are under the transcriptional control of the AR." (PMID 36674430, 2023). "Whereas the biological role of FASN is known, its response and sensitivity to inhibition have not yet been fully established in these two cancer settings." (PMID 36650542, 2023). "Several studies have shown that the inhibition of FASN can lead to the compensatory upregulation of CD36 expression and that inhibiting both pathways is lethal to cancer cells, highlighting the essentiality of FA pool maintenance in cancer." (PMID 37371076, 2023). "Five cancer-derived hot spot mutants of FBXW7β (M1–M5 located in WD40 domain of FBXW7β, see 3D structure) were constructed for examining their impacts, especially on FASN expression." (PMID 37202390, 2023). "Upregulation of FASN can increase the synthesis of SFA and MUFA, and high saturated levels of membrane lipids protect cancer cells from ROS-induced damage, thus preventing and repairing sorafenib induced lipid peroxidation and responsible for sorafenib resistance." (PMID 36604718, 2023). "For example, statins (inhibitors of cholesterol synthesis) are currently tested in multiple clinical trials as anti-cancer agents, and TVB-2640, an inhibitor of FASN, is currently evaluated in six clinical trials either as a single agent or in combination with others." (PMID 36839759, 2023). "Although this study demonstrates that miR-127 also downregulates other genes that are overexpressed in cancer, such as FOXO6, SOX11, SOX12, and FASN, it provides the first example that targeting NANOS1 could be a potential cancer treatment strategy." (PMID 36012673, 2022). "Fatty acid synthase (FASN), one of the key enzymes in the DNL pathway involved in saturated long chain fatty acid synthesis, is expressed at low levels in normal cells, but increased levels have been reported in various cancer cells." (PMID 35243817, 2022). "SREBPs transcriptionally activates enzymes involved in lipogenesis processes in cancer cells, including ATP citrate lyase (ACLY), acetyl-CoA carboxylase (ACC), fatty acid synthase (FASN), and acyl-CoA synthetase (ACS) which play significant roles in the process of lipid biosynthesis." (PMID 35646898, 2022). "Interestingly, some enzymes associated with fatty acid synthesis, including ATP citrate lyase, Acetyl-CoA carboxylase (ACC) and fatty acid synthase (FASN), are upregulated in some cancers." (PMID 36230935, 2022).
cancer (continued). "Saturated and monounsaturated fatty acids (SFAs and MUFAs) are part of de novo biosynthesis involving the enzyme complex fatty acid synthase (FASN) and delta-9-desaturase activity (∆9D, stearoyl-CoA desaturase, SCD-1); both of these enzymes are subject to overexpression in cancer." (PMID 35206081, 2022). "Increased FASN, CPT1B, and CD36 expression correlate with poor drug response in cancer patients." (PMID 35764645, 2022). "FA synthesis and metabolism play vital roles in cancer immunogenicity and immunotherapy, since FASN is a central member of FA metabolism processes, and no studies have reported the connection between FASN alterations and ICI therapy efficacy." (PMID 36428733, 2022). "Dysregulation of critical genes (such as ACACA, FASN, and CPT1A) in fatty acid metabolism, leading to an imbalance in fatty acid degradation and production, was considered as a potential metabolic marker for cancer cells." (PMID 35076025, 2022). "In addition to cholesterol metabolism and FASN-mediated fatty acid synthesis, lipid droplets also depend on TGF-β signaling in cancer cells." (PMID 36115986, 2022). "In addition, six genes are involved in cancer and inflammatory processes (YWHAZ, CCL2, and SMPD2) and lipid droplet formation and metabolism (CIDEC, VLDLR, and FASN) and were significantly increased in NASH patients." (PMID 36612019, 2022). "In tumor cells, 90% of fat synthesis source from the catalysis of FASN, and the proliferation of cancer cells requires the synthesis of biofilms, so it is no wonder that lipid synthesis is metabolically abnormal in tumor cells." (PMID 35743814, 2022). "Moreover, FASN inhibitors have antilymphangiogenic effects, decreasing LEC viability, proliferation, and migration, thereby impairing cancer cell lymphatic metastasis." (PMID 36232355, 2022). "The results showed a strong correlation between FASN expression and MSI in twelve cancers." (PMID 36555243, 2022). "There were no significant changes in FASN expression that would indicate enhanced de novo synthesis of fatty acids in cancer cells." (PMID 36012230, 2022). "Whereas FASN has been a subject of intense research, the other fatty acid-related genes have not been studied for their role in cancer." (PMID 36516496, 2022). "Besides that, number of new-generation FASN inhibitors have been developed recently including TVB-2640, which is now in clinical trials in cancer (NCT02223247)." (PMID 36582801, 2022). "EGCG inhibits FASN activity, which promotes apoptosis in cancer cells, in the same way that FASN inhibitor C75 does, but with less negative effects." (PMID 35243817, 2022). "Second, association of FASN mutations with ICI efficacy was discovered and confirmed only in two cancer types, and no additional cancers are available." (PMID 36428733, 2022). "In contrast, given the negative regulatory mechanism of “miRNA-Target”, we chose mir-195-5p and mir-497-5p, which have a negative correlation with FASN and are typically decreased in cancer for further investigation." (PMID 36555243, 2022). "FASN expression is regulated by the PI3K/Akt axis, which is frequently dysregulated in cancer." (PMID 35268652, 2022). "Cerulenin, a specific FASN inhibitor, suppresses the expression of HER2/neu in cancer." (PMID 35216285, 2022). "Therefore, fatty acid synthesis (FAS) inhibitors, especially fatty acid synthase (FASN), have been the focus of cancer treatment studies." (PMID 36591293, 2022). "Various studies have shown that FASN inhibitors such as epigallocatechin gallate (EGCG), C75, and cerulenin could specifically induce cancer cell apoptosis." (PMID 35566090, 2022). "To date, the roles of FASN alterations in cancer immune checkpoint inhibitor (ICI) treatment have never been reported." (PMID 36428733, 2022). "Additionally, with the overexpression of fatty acid synthase (FASN), cancer cells highly produce lipids for membrane biosynthesis, and as cholesterol and fatty acid deposits for energy and signaling." (PMID 33664364, 2021).
cancer (continued). "Fatty acid synthase (FASN) is the enzyme involved in endogenous fatty acid synthesis, which is crucial for the formation of membrane lipids and sustains redox equilibrium and the relative levels of saturated and unsaturated fatty acids in cancer cells." (PMID 34150624, 2021). "Inhibition of USP14 by IU1 or siRNAs targeting USP14 did not reduce FASN levels but rather increased FASN levels and activity in cancer cells." (PMID 34948233, 2021). "Consistently, our data show that MIEF2 promoted the de novo fatty acid synthesis of OC cells through up-regulation of the lipogenic enzymes of ACC1, FASN and SCD1, which further support the oncogenic role for dysregulated lipogenic enzymes in the promotion of cancer progression." (PMID 33414447, 2021). "Since lipid molecules such as phospholipids are important for forming cell membranes, it is not surprising that FASN is overexpressed in various cancer cells, promoting their rapid proliferation." (PMID 34948233, 2021). "Cancer cells activate de novo lipogenesis by upregulating several enzymes involved in the pathway, specifically acetyl-CoA carboxylase (ACC), fatty acid synthase (FASN), and stearoyl-CoA desaturase 1 (SCD1)." (PMID 33946927, 2021). "Dihydroartemisinin treatment significantly reduces the expressions of c-Myc and its downstream targets ACC, FASN, CPT-1, and MCAD, which changes the lipid metabolism and the metabolic phenotypes in CRC, reduces energy production, cell proliferation, and induces cancer-cell death." (PMID 34741022, 2021). "Unfortunately, high in vitro sensitivity of cancer cells to FASN inhibitors does not always lead to high in vivo sensitivity." (PMID 33928023, 2021). "These two main methods of FASN regulation do not have to be mutually exclusive; it is also possible that they take place concurrently in cancer cells." (PMID 33208446, 2021). "The expression of FASN is significantly upregulated in many cancer types while it is extremely low in nonmalignant tissues." (PMID 32695216, 2020). "Similarly, CAFs in CRC accumulated fatty acids and phospholipids via an increase in fatty acid synthase (FASN), and were then transferred to cancer cells to induce their migration." (PMID 32760726, 2020). "In general, PCa-associated exosomes procured from clinical samples reveal cargo that contains cancer-related proteins such as CD9, CD81, and TSG101, Annexin A2, Fatty Acid Synthase (FASN), and prostate-specific membrane antigen (PSMA: a PCa-specific biomarker)." (PMID 32121073, 2020). "Fatty acid synthase (FASN), a key enzyme required for the synthesis of fatty acids and precursors of certain biologically important lipids, is the most well-investigated lipogenic protein in cancer research." (PMID 32699531, 2020). "Furthermore, FASN is identified a suitable target for GBM treatment and it was, in fact, demonstrated that its inhibition led to programmed cell death in cancer cells." (PMID 31936544, 2020). "Cancer cells develop capable de novo FAS machinery with an increase in the activity of key lipogenic enzymes such as adenosine triphosphate (ATP)-citrate lyase (ACLY), acetyl-CoA carboxylase (ACC), CoA carboxylase (ACACA), fatty acid synthase (FASN), and SCD." (PMID 33364199, 2020). "FASN inhibitors from TVB appear to be safe in humans and reduced lipogenesis in small clinical studies as a single agent and demonstrate some efficacy in patients with cancer." (PMID 33083663, 2020). "FASN inhibitors from TVB appear to be safe in humans and reduce lipogenesis in small clinical studies as a single agent, in addition to demonstrating some efficacy in patients with cancer." (PMID 33083663, 2020). "The predicted estimation of being diagnosed with cancer from the log it model based on the five selected lipogenic genes panel, and Log it (P) = 0.429 + 0.659 x ACOT8 + 0.084 x ACSL5 + 0.029 x FASN + 0.201 x HMGCS2 + 0.119 x SCD1 was used to create the ROC curve." (PMID 32155177, 2020).
cancer (continued). "Fatty acid synthase (FAS) is a key enzyme involved in de novo lipogenesis that produces lipids that are necessary for cell growth and signal transduction, and it is known to be overexpressed, especially in cancer cells." (PMID 33182594, 2020). "Down-regulation of SREBP-1 and/or FASN using sequence-specific miRNAs (miRNA-185 and 342) or selective small compounds (IPI-9119, orlistat, and fatostatin) has been reported to inhibit cell growth, survival and progression in cancers." (PMID 32276528, 2020). "The overexpression of HER2 is sufficient to prompt a FASN-dependent lipogenic phenotype in non-transformed epithelial cells that recapitulate the cancer cell metabolism." (PMID 32486505, 2020). "New reports have given to FASN a central role in supporting cancer cell growth rather than functioning as an anabolic energy-storage pathway." (PMID 30962418, 2019). "FASN plays a major role in FAS and has been shown to be upregulated in different cancer cells." (PMID 30962418, 2019). "A very important finding from this study is that the importance of FASN for cancer development is independent of its biosynthetic product." (PMID 31676791, 2019). "In another report, low concentration of metformin (60 μM) in combination with genistein (2 μM) and lunasin (2 μM), increased the PTEN expression, inhibited the cancer stem cell-like cells CD133+CD44+ subpopulation, and reduced fatty acid synthase (FASN) expression in HCT116 cells." (PMID 31831021, 2019). "We and other groups also found that either the imbalanced circulating cholesterol or upregulated expression of FASN, ACACA and SREBPs correlated with a poorer diagnosis in different cancers, implying a significance of the lipid metabolism during the cancer development in clinic." (PMID 31416244, 2019). "Based on these results, we proposed that SK1 protein expression, as opposed to other differentially expressed species in the cancer groups like actin and FASN, was post-transcriptionally elevated in the PDAC subclones." (PMID 30728898, 2019). "De novo synthesis of FA is activated in cancer cell, which is catalyzed by ATP citrate lyase (ACLY), acetyl-CoA carboxylase (ACC) and fatty acid synthase (FASN), then converted to monounsaturated FA (MUFA) to generate triacylglycerol (TAG), the composition of LDs, by stearoyl-CoA desaturase (SCD)." (PMID 31777589, 2019). "Moreover, IGF1R, TNPO1 and FASN are experimentally validated targets for TFAP2A, as annotated by RegNetwork software, and are involved in multiple cancer stemness and drug resistance processes." (PMID 30944375, 2019). "Dysregulation of fatty acid metabolism in cancer cells is well known as it is the potential of fatty acid synthase (FAS) as a drug target; in fact, FAS was expressed above normal in MM and CLL." (PMID 31248049, 2019). "Fatty acid synthase (FASN) is overexpressed in most human carcinomas, including non-small cell lung cancer (NSCLC), and contributes to poor prognosis." (PMID 31122252, 2019). "The authors showed that FASN is overexpressed and is more sensitive to inhibition by cerulenin in Panc1 CSCs than in the parental non-stem cancer cells." (PMID 29907133, 2018). "Fatty acid synthase (FASN) upregulated by human epidermal growth factor receptor 2 (Erb-B2) (also known as HER/neu), a tyrosine kinase receptor, is frequently overexpressed in cancer cells, which promotes their invasiveness and proliferation." (PMID 30416487, 2018). "Although increased lipogenesis has been well documented in CSCs from various cancer types, most chemical compounds targeting FASN does not show a therapeutic efficacy in pre-clinical cancer models and only one FASN inhibitor has entered clinical trials." (PMID 29907133, 2018). "However, inhibition of FASN also induces pro-survival Akt and ERK signaling in K-Ras-driven cancer cells." (PMID 29872506, 2018). "The expression of FASN is independent of nutrition, in many cancers, as well as independent of hormonal regulation." (PMID 28421159, 2017).
cancer (continued). "Notably, the expression of the lipogenic enzymes FASN and ACC are downregulated in circulating cancer cells, when compared to their primary cancer counterpart." (PMID 28352611, 2017). "Lipogenic enzymes, such as FASN, ACC, and ACLY that are required for fatty acid biosynthesis, and SREBP1, the master regulator of lipogenic gene expression, are overexpressed in many cancers, including breast." (PMID 28421159, 2017). "In addition, GA inhibited de novo lipogenesis in cancer cells by activating AMPK signaling and lowering the expression of enzymes involved in lipogenesis, including acetyl-CoA carboxylase (ACC), fatty acid synthase (FASN)." (PMID 28402272, 2017). "A very limited number of reports (2–4 out of 11) identified the mRNAs in EVs from different cancer and non-cancerous cell sources, with the exception of FASN, which was found in 6/10 studies." (PMID 28143451, 2017). "Thus by interacting with a potential integrative metabolic mediator FASN, OPG can indirectly modulate the metabolism and modification of proteins in an aggressively dividing cancer cell." (PMID 27270654, 2016). "The elevation of FASN expression in cancer is consistent with evidences that metabolism of arachidonic acid (AA) by the COX pathway is upregulated, which plays important roles in inflammation and cancer progression." (PMID 27270654, 2016). "While the upregulation of FASN is well documented in cancer cells, we did not observe a significant change in metastatic cells." (PMID 26725848, 2016). "There is a strong link between FASN and the cyclooxygenase (COX) pathway in cancer." (PMID 27270654, 2016). "Previously, we have found that, independent of its kinase activity, EGFR interacts with FASN at the plasma membrane in cancer cells." (PMID 26378037, 2015). "However, cancer grade (p = 0.000) and FIGO staging (p = 0.000) were significantly correlated with FASN expression." (PMID 25433947, 2015). "The significant role of FASN and ACC in cancer development has been well established in the past." (PMID 25895130, 2015). "We found, for instance, that 6 cancer-related targets changed their expression levels: HSPD1, PARP1, XRCC5, PRDX2, MTA2 and FASN." (PMID 24801752, 2014). "FASN is the downstream mediator of HER2 tumorigenicity and cancer progression." (PMID 24866893, 2014). "Indeed, several studies have reported direct relationships between expression and activity of FASN and HER2 signaling pathway activation, which notably affected Akt and Erk activity in cancer cells." (PMID 25472762, 2014). "The dual activity of orlistat, reducing dietary lipid absorption and as an inhibitor of FASN, could also have an adjunct role to play in mitigating the side effects of ADT which may promote cancer progression." (PMID 23573093, 2013). "Furthermore, the overexpression of genes involved in fatty acid synthesis, such as the fatty acid synthase (FASN), acetyl-CoA carboxylase alpha (ACACA) and, the ATP citrate lyase (ACLY) can induce the development and progression of cancer." (PMID 24958265, 2013). "Despite the fact that FASN overexpression has been observed in different forms of cancer, there is still no clear mechanism explaining how FASN mediates its oncogenic effects." (PMID 22485149, 2012). "EGCG acts as potent and lipogenic-selective inhibitor of FASN, and do no exhibit adverse effects on body weight, therefore holding promise for further target-directed anti-cancer drug studies either alone or co-administered with other antitumoural drugs." (PMID 22769244, 2012). "Furthermore, lipogenic enzymes that function upstream of FASN such as acetyl-CoA carboxylase-a (ACACA) and ATP citrate lyase (ACL) are also elevated in various cancers." (PMID 22266777, 2012).